HOTAIR (HOX transcript antisense RNA)
Diseases named in the same sentence as HOTAIR in open-access papers (continued):
Sharing a sentence is not in itself a finding about the gene and the disease.
cancer (continued). "HOTAIR have abnormal expression in the different human cancers." (PMID 30873206, 2019). "In addition, numerous experimental evidences have focused the attention on the potential role of HOTAIR as a circulating marker and therapeutic target for cancer patients." (PMID 31072041, 2019). "Furthermore, HOTAIR upregulates c-Myc in breast and ovarian cancers, which in turn promotes cancer cell proliferation." (PMID 31208095, 2019). "It is clear that HOTAIR promotes cancer cell migration and invasion." (PMID 31171714, 2019). "In effect, down-regulation of HOTAIR provides new insights for cancer treatment." (PMID 31171714, 2019). "Different studies describe the role of HOTAIR in the hypoxic microenvironment of human cancers." (PMID 31072041, 2019). "In addition, HOTAIR overexpression reduced the inhibitory effects of PTCSC3 overexpression on cancer cell proliferation." (PMID 31171714, 2019). "Our date enriched our understanding on the functionality of HOTAIR in cancer biology and suggested that overexpression of PTCSC3 may serve as a therapeutic target for LSCC." (PMID 31171714, 2019). "On the basis of our findings, HOTAIR represents a potential powerful predictor of prognosis of overall survival, cancer recurrence, progression, and metastasis in multiple and diverse types of cancers." (PMID 31195674, 2019). "The reported “circulating miRNAs” and plasma lncRNAs or lncRNAs such as HOTAIR, metastasis-associated lung adenocarcinoma transcript 1 (MALAT1), H19, and GAS5 might also have value in the evaluation of radioresistance in cancer patients." (PMID 31174564, 2019). "A positive correlation between HOTAIR and CDKN1A (p21) expression levels was also found, suggesting a possible functional and/or physical association between HOTAIR and CDKN1A (p21) in cancer pathophysiology." (PMID 31195674, 2019). "Numerous lncRNAs, including HOTAIR, are found in EVs derived from different cancer cells." (PMID 31072041, 2019). "And one of the deepest and broadest studied PRC2 interacting lncRNA is HOTAIR, which is deregulated in diverse cancers and could be an independent and powerful predictor of eventual metastasis and death." (PMID 30764859, 2019). "Furthermore, HOTAIR is suggested to promote cancer progression and contribute largely to cancer cell invasion and metastasis." (PMID 31195674, 2019). "HOTAIR is among the first lncRNAs reported to be involved in the development of cancer." (PMID 31480503, 2019). "Likewise, a lot of previous meta-analyses investigated the relationship between the other lncRNAs expression and prognosis of corresponding cancers, such as HOTAIR, H19 and MALAT1." (PMID 29805767, 2018). "HOTAIR is responsible for regulating epigenetic cellular memory and cancer development." (PMID 29721215, 2018). "Importantly, methylation signatures acquired from tumours exhibiting altered HOTAIR expression have been predicted to function as a biomarker for poor prognosis in various cancers and therapy resistance." (PMID 29732012, 2018). "Importantly, we discovered that the lncRNA HOTAIR known to be involved in the epigenetic regulation of cancer progression is only expressed at appreciable levels in GF-fat and isolated preadipocytes from GF." (PMID 30477572, 2018). "Studies have shown that HOTAIR was involved in cancer invasion and metastasis." (PMID 29707567, 2018). "Although several lncRNAs alter their expression levels in cancer cells, only HOTAIR and MALALT-1 detected in the saliva has statistically difference and may act as a rapid and noninvasive diagnostic strategies." (PMID 29416703, 2018). "Furthermore, lncRNAs are important factors in the control of gene expression in cancer, and lncRNAs such as HOTAIR have been shown to play a significant role in the development and progression of tumors." (PMID 29433566, 2018).
cancer (continued). "Works pioneered by Howard Chang and colleagues has uncovered a compelling mechanistic basis for HOTAIR in cancer, which interacts with the polycomb repressive complex 2 (PRC2) to enhance H3K27 trimethylation, and decreases the expression of a large number of genes." (PMID 29391067, 2018). "lncRNA HOTAIR has been used as a prognostic marker in different cancer types." (PMID 30069164, 2018). "Rs7958904 genetic polymorphism, which is located on the exon of HOTAIR gene, we identified the SNP significantly decreased susceptibility to overall cancer risk in all genetic models rather than recessive and homozygous models." (PMID 29463216, 2018). "HOTAIR also could form regulation network of ceRNAs with miRNA to participate in carcinogenesis of different cancers." (PMID 29463216, 2018). "In the final analysis, HOTAIR was intricately related to various cancers." (PMID 29463216, 2018). "HOTAIR interacts with chromatin modeling complexes, which consequently leads to gene regulation and the promotion of tumor cell invasion, metastasis, and maintenance of stemness in cancer cells." (PMID 30483476, 2018). "While MKL1 nearly showed the same expression trend with HOTAIR in the cancer tissues." (PMID 29391067, 2018). "As an oncogene, HOTAIR is overexpressed in many cancer and involved in cancer proliferation, migration, invasion, progression and poor prognosis, suggesting that it might be a potential novel target in cancer therapy." (PMID 27965458, 2017). "HOX antisense intergenic RNA (HOTAIR), a lncRNA encoded by a gene located in the mammalian HOXC locus, binds to the polycomb repressive complex 2 (PRC2), a histone methyltransferase required for epigenetic silencing during development and cancer." (PMID 28671581, 2017). "Depletion of HOTAIR induces cell-cycle arrest in various cancer types." (PMID 28811863, 2017). "In addition, it has very recently been established how lncRNA HOTAIR is functionally involved in lung tumor progression through PRC2, and how is epigenetically associated to cancer-drug cisplatinum resistance mechanisms." (PMID 28904641, 2017). "Many studies point at miR-34a as a major component of HOTAIR–miRNAs–cancer cross-talk." (PMID 29469819, 2017). "Given that lncRNAs can act as miRNAs sponge to promote the development of cancers, we presumed that HOTAIR might contribute to Bcl-w elevation by sequestering miRNAs." (PMID 29222472, 2017). "Due to results indicating an important role in cancer, HOTAIR is one of the most studied lncRNAs." (PMID 29069846, 2017). "The high expression of lnc-HOTAIR can promote the proliferation, migration and invasion of tumor cells, while the unlimited proliferation of cells is closely related to the occurrence and development of cancer." (PMID 28388563, 2017). "Thus, increased HOTAIR expression promotes cancer progression, and HOTAIR functions as an oncogene in HNC." (PMID 27802187, 2017). "We believe that the differential expression of HOTAIR may indicate the potential role of this lncRNA in cancer initiation and progression." (PMID 29209357, 2017). "HOTAIR can promote cancer cell metastasis by reprogramming chromatin organization." (PMID 28177890, 2017). "Moreover, we also selected five representative disease lncRNAs (HOTAIR, MALAT1, H19, MEG3 and TUG1) that play key roles as oncogenic molecules associated with various cancers to investigate their occurrences at the top 5%-20% of the candidate lists." (PMID 28076842, 2017). "Treatment of A2780_CR5 cells with PNA3 decreased (25%) ALDH1A1 activity, suggesting HOTAIR inhibition with PNA could reduce the cancer stem cell population." (PMID 28420874, 2017). "Thus, in the meta-analysis, we mainly focus on evaluating the association between HOTAIR, PRNCR1, H19, POLR2E polymorphisms and cancer risk." (PMID 28159929, 2017).
cancer (continued). "Dysregulated expression of HOTAIR, which promotes metastasis in several cancer types, is often found in human cancers, e.g., melanoma, breast, hepatocellular, gastric, colorectal or pancreatic carcinoma, and its expression is correlated with poor prognosis, e.g., in colorectal cancers." (PMID 29125541, 2017). "Additionally to cancer, HOTAIR expression is also detected in gluteal adipose tissues, with enrichment in adipocyte fractions, suggesting its potential role in adipogenic differentiation." (PMID 29137239, 2017). "Therefore, serum HOTAIR expression level can serve as the indicator for cancer recurrence of ESCC patients who undergo tumor resection." (PMID 28376832, 2017). "As the knockdown induced upregulation of many other genes important for cancer transformation, it was concluded that the role of increased expression of HOTAIR in tumorigenesis could result from its inhibition of tumor suppressors." (PMID 29469819, 2017). "HOTAIR can be also regarded as an oncogene and promotes cancer metastasis." (PMID 28177890, 2017). "The association between HOTAIR expression and clinical tumor stage could be detected in patients by qRT-PCR and ISH, suggesting that HOTAIR has the potential to be a stable predictor to evaluate cancer progression." (PMID 28591050, 2017). "Since our results showed that HOTAIR regulates cancer invasiveness and metastasis both in vitro and in vivo, we identified invasiveness-related genes that were upregulated in our microarray data for HOTAIR-overexpressing cells and were reported to be potentially oncogenic." (PMID 28931862, 2017). "Importantly, it was demonstrated that the control of EMT through HOTAIR contributes to the emergence and maintenance of cancer stem cells (CSCs)." (PMID 28671581, 2017). "Furthermore, HOTAIR can function as a competitive endogenous RNA (ceRNA) in cancer cells, recruiting microRNAs to target various genes." (PMID 29108287, 2017). "We examined the cancer stemness and invasiveness in vitro and tumorigenicity in xenotransplantation model and demonstrated that modulation of HOTAIR could be considered for the development of CSC-targeted therapy in oral carcinogenesis." (PMID 29228709, 2017). "In addition to promoting cancer progression and initiation, recent evidence indicates an important role of HOTAIR in radiotherapy for cancer." (PMID 28872613, 2017). "Additionally, lncRNA Hox transcript antisense intergenic RNA (HOTAIR) promotes metastasis by increasing cell proliferation, migration, and the invasion of cancer cells, and the CxCa patients with high levels of HOTAIR often have a poorer prognosis." (PMID 29312619, 2017). "The lncRNAs have been proved to engage in cancer metastasis such as HOTAIR, MALAT1 and HULC." (PMID 28969031, 2017). "In addition, the HOTAIR expression is exponentially increases with progression in clinical stage and finally high expression of HOTAIR is correlated with a poor prognosis of cancer." (PMID 28039476, 2017). "HOTAIR is deregulated in many human cancers; despite its critical roles in health and disease, the underlying mechanisms governing HOTAIR function are unknown." (PMID 28649178, 2017). "The role of HOTAIR in RCC cancer growth was examined in vivo." (PMID 28938586, 2017). "HOTAIR has been known to play an important role in various cancers, and genome-wide analysis indicates that it may, at least in part, be mediated by HOTAIR targeting the PRC2 complex to specific genes." (PMID 27659532, 2016). "For the first time, we explain the molecular mechanism of the apoptosis induced by HOTAIR knockdown and this multi-layer modulation might be valuable in cancer treatment strategy exploration." (PMID 26962687, 2016). "Since then, HOTAIR was evaluated as an oncogenic factor and could be used as a prognostic biomarker in different cancer type." (PMID 26967389, 2016). "HOTAIR was overexpressed from 2- to nearly 1,600-fold in the cancer tissues." (PMID 27686732, 2016).
cancer (continued). "Thus, abundant lncRNAs such as H19, Urothelial Carcinoma Associated 1 (UCA1), HOTAIR, MALAT1, and HIF1A-antisense transcript (HIF1A-AS) are attractive as potential biomarkers and/or therapeutic targets in cancer." (PMID 26590207, 2016). "Several studies indicated that the expression of HOTAIR frequently changes during malignant transformation and may be a key molecule in breast carcinogenesis and cancer progression, with the potential to serve as a novel biomarker and therapeutic target." (PMID 27388461, 2016). "Accumulating evidence indicates that HOTAIR plays a critical role in cancer progression." (PMID 27367027, 2016). "Moreover, Enforced expression of HOTAIR altered histone H3 lysine 27 methylation, gene expression, and increased cancer invasiveness in a manner dependent on Polycomb Repressive Complex 2 (PRC2)." (PMID 27367027, 2016). "Moreover, HOTAIR, a cancer-related long non-coding RNA is discovered to be up-regulated in NPC and associated with poor prognosis as well." (PMID 27170279, 2016). "Recent studies have demonstrated that lncRNAs are involved in the development of different types of cancer, for example, metastasis associated lung adenocarcinoma transcript 1 (MALAT-1) in non small cell lung cancer and HOTAIR in breast cancer and colorectal cancer." (PMID 27751178, 2016). "We chose five lncRNAs (HOTAIR, HOXA-AS-2, lincRNA—ROR, MALAT1, and ANRIL) and three mRNA Homeobox A13 (HOXA13), SRY-box 2 (SOX2) and POU class 5 homeobox 1 (POU5F1/OCT4) implicated in a range of cancers, including UBC." (PMID 26800519, 2016). "All these studies suggest that changes in HOTAIR expression may impact the expression of multiple genes by the loss of cooperation with PRC2 complex, resulting in an increase of undifferentiated cancer cells." (PMID 27148353, 2016). "Numerous studies have demonstrated that overexpression of HOTAIR occurs in many cancers." (PMID 27246974, 2016). "Thus, although the sample sizes of other leading cancers were small, this result implies that salivary HOTAIR and PVT1 show potential to be a novel and specific biomarker for PC." (PMID 27028998, 2016). "In cancer cells, HOTAIR partners with PRC2 to induce genome-wide gene silencing." (PMID 27686732, 2016). "In order to find out whether HOTAIR is essential for cancer cell survival, we transfected a specific siRNA targeting HOTAIR (siHOT1) or scrambled siRNA (siNC) into HCT116, HeLa, HepG2, A549 and DU145 cells." (PMID 26962687, 2016). "HOTAIR was one of the first oncogenic lncRNA reported to be involved in cancer progression through genome-wide epigenetic reprogramming, through the interaction with polycomb repressive complex 2 (PRC2) subunits, a key chromatin remodeling complex involved in gene silencing." (PMID 27340923, 2016). "Emerging evidence indicates that dysregulated long intervening non-coding RNA (lincRNA) HOTAIR correlates highly with tumor invasion and metastasis but a link between the high expression of HOTAIR and the metastatic cascade of cancer stem cells (CSCs) needs to be further studied." (PMID 25792974, 2015). "Taken together, HOTAIR plays a critical role in human cancers by inhibiting miRNAs." (PMID 26183397, 2015). "HOTAIR is becoming a potential therapy target in many cancers." (PMID 25928008, 2015). "The identification of HOTAIR may provide a clue to further understanding how lncRNAs regulate the responsiveness of cancer cells in response to cancer treatments." (PMID 25883211, 2015). "Therefore, to investigate the way HOTAIR regulates cells is very important for cancer clinical therapy." (PMID 25928008, 2015). "Thus, HOTAIR functions and target genes cannot simply be transferred from one cancer type to the other." (PMID 25994132, 2015). "In addition, measuring the expression level of HOTAIR can help us detect the progression stage of cancer and predict the survival possibility of an individual." (PMID 25859406, 2015).
cancer (continued). "In addition, screening the HOTAIR overexpression can help us identify cancer progression and tumor stage." (PMID 25859406, 2015). "To further understand the physiological role of HOTAIR in lung ADC cells, we generated stable HOTAIR knockdown in PC9 cancer cells using a set of shHOTAIR lentivirus vectors (see ‘Materials and Method’ section) and observed about 70% of reduction in HOTAIR levels." (PMID 26658322, 2015). "HOTAIR has been characterized as a molecule involved in cancer cell invasion." (PMID 25823657, 2015). "In view of the causal relevance of the viral oncoprotein E7 in CaCx pathogenesis, we further explored the interplay between E7 and HOTAIR in order to explore if HOTAIR could be targeted by E7 to achieve up-regulation of cancer related pathway genes." (PMID 26152361, 2015). "This fingings suggested that the streatgy of down-regulating the HOTAIR expression may serve as a potential anti-cancer regimen for inhibiting EOC CSC’s invasiveness and metastasis." (PMID 25792974, 2015). "We therefore wondered whether the findings in other cancers on expression and function of HOTAIR could be extended to UC, in particular with regard to the regulation of aberrant differentiation patterns and HOX gene expression." (PMID 25994132, 2015). "HOTAIR has been shown to be upregulated in cancer tissues and metastases, and its expression level correlates in general with metastasis and poor outcome in multiple cancer types." (PMID 26457124, 2015). "The lncRNA HOTAIR is a critical regulator of cancer progression." (PMID 26658322, 2015). "The expression of HOTAIR was found to be upregulated in cancer tissues from 95 CRC patients." (PMID 26307974, 2015). "Strategies to reduce HOTAIR activity (i.e., by intra-peritoneal HOTAIR small interfering RNA) may lead to a novel strategy to (re)sensitize cancers to chemotherapy." (PMID 26497652, 2015). "Previous study have shown that HOTAIR could alter histone H3 lysine 27 methylation, and increase cancer invasion and metastasis in a manner dependent on PRC2 by form a complex with Polycomb repressive complex 2 (PRC2)." (PMID 26183397, 2015). "Furthermore, we found reactivation of HOXD12 and HOXD13 expression in selected cancer samples and, surprisingly, a strong positive correlation between HOTAIR and HOXD12, particularly in overexpressing UC tissues (r Pearson = 0.92)." (PMID 25994132, 2015). "Although these observations concur with those in other cancer types, we have observed that HOTAIR target genes cannot be generalized from one tissue to another and may even differ between individual cancers of the same type." (PMID 25994132, 2015). "MALAT1 and HOTAIR are both examples of lncRNAs which are deregulated in the majority of cancers." (PMID 26516918, 2015). "HOTAIR is aberrantly expressed in several carcinomas, including NPC." (PMID 26448942, 2015). "Moreover, up-regulated expression of HOTAIR is an indicator of poor prognosis in many other kinds of cancers." (PMID 25334066, 2014). "Through subgroup analysis, we identified for the first time that HOTAIR was a novel predictive factor for poor prognosis in different types of cancers for both Western and Asian populations; however, HOTAIR was an independent prognostic factor for OS of Asian patients rather than Western ones." (PMID 25157956, 2014). "HOTAIR expression has been investigated in tumor samples from many different cancer types." (PMID 25275300, 2014). "HOTAIR was shown to promote invasiveness and proliferation of cancer cells." (PMID 24953832, 2014). "HOTAIR abundance may serve as a novel predictive factor for poor prognosis in different types of cancers in both Asian and Western countries." (PMID 25157956, 2014). "Additionally, HOTAIR with a half-life < 4 h in human Hela cells, has active role in modulating the cancer epigenome by binding to the polycomb repressive complex 2 (PRC2)." (PMID 24996425, 2014).